EXOC4 (exocyst complex component 4)
Description:
Component of the exocyst complex involved in the docking of exocytic vesicles with fusion sites on the plasma membrane.
Synonyms: KIAA1699; SEC8; SEC8L1; MGC27170; Sec8p
Tractability: Antibody: its Gene Ontology location is reachable by antibodies, with high confidence. PROTAC: ubiquitination databases record sites on it; its protein half-life has been measured.
Safety:
Unwanted effects reported when the protein is acted on. In parentheses: how it was acted on, where the effect was seen, and who reports it.
opioid dependence (source: ClinPGx)
Gene: Protein-coding gene on chromosome 7 (133,253,071 to 134,067,137, forward strand). Ensembl gene ENSG00000131558.
Subcellular location: Midbody, Midbody ring; Cell projection; Cytoplasm, cytoskeleton, microtubule organizing center, centrosome
Pathways (Reactome):
Metabolism of proteins: Insulin processing
Organelle biogenesis and maintenance: VxPx cargo-targeting to cilium
Vesicle-mediated transport: Translocation of SLC2A4 (GLUT4) to the plasma membrane
Gene Ontology:
Molecular function: protein binding; GTP-dependent protein binding; PDZ domain binding
Biological process: chemical synaptic transmission; exocytosis; Golgi to plasma membrane transport; membrane fission; mitotic cytokinesis; regulation of macroautophagy; cilium assembly; protein localization to ciliary membrane
Cellular component: 9+0 non-motile cilium; centrosome; ciliary shaft; cytoplasm; membrane; cytosol; exocyst; growth cone membrane; plasma membrane; synapse; Flemming body; microvillus; myelin sheath abaxonal region
Genetic constraint (gnomAD): Loss-of-function variants: 57 observed, 95.37 expected, observed/expected ratio (o/e) 0.6, 90% interval 0.48 to 0.75. The upper end of that interval is the gene's LOEUF score, 0.75, which puts it in group 3 of 6, group 1 being the genes least tolerant of losing a copy. Missense variants: 996 observed, 1,130.8 expected, observed/expected ratio (o/e) 0.88, 90% interval 0.83 to 0.93. Synonymous variants: 409 observed, 416.22 expected, observed/expected ratio (o/e) 0.98, 90% interval 0.9 to 1.07.
Homologues: Orthologues: chimpanzee EXOC4 (99% identical), macaque EXOC4 (99% identical), dog EXOC4 (97% identical), guinea pig EXOC4 (96% identical), mouse Exoc4 (96% identical), rat Exoc4 (95% identical), tropical clawed frog exoc4 (87% identical), zebrafish exoc4 (80% identical), Drosophila melanogaster Sec8 (34% identical), Caenorhabditis elegans sec-8 (26% identical).
Diseases named in the same sentence as EXOC4 in open-access papers:
EXOC4 is named in the same sentence as 34 diseases in open-access papers, as found by Europe PMC text mining. Sharing a sentence is not in itself a finding about the gene and the disease. The quoted sentences say what the papers report.
type 2 diabetes (7 papers, 2008 to 2024). "INPP4B protects against metabolic syndrome and associated disorders and EXOC4 is involved in insulin-stimulated glucose transport and is associated with type II diabetes and fasting glucose." (PMID 38483771, 2024). "A population genetic study also identified several type 2 diabetes-associated SNPs near EXOC4 in The NHLBI Family Heart Study." (PMID 31118946, 2019). "Another gene EXOC4 (SEC8L1), which contains a polymorphism associated with type 2 diabetes was also frequently deleted in our samples, and is known to play a role in synaptogenesis and brain development." (PMID 20126641, 2010). "However, some of these variably erased CGIs (VECs) remained methylated at all stages, including in mature oocytes and sperm, for example a CGI in the Exoc4 gene which is associated with type 2 diabetes and involved in insulin-stimulated glucose transport." (PMID 23219530, 2012). "EXOC4 is located in a widely replicated obesity linkage peak on chromosome 7q22-q36, and has been connected with various diseases, such as type 2 diabetes, cancer, and neuronal disorders." (PMID 31118946, 2019). "Not much is known about EXOC4 except that adjacent polymorphisms were associated with Type 2 diabetes." (PMID 31892232, 2019). "Just like the polymorphism between EXOC4 and LRGUK, AHCYL2 is associated with type 2 diabetes." (PMID 27589727, 2016).
schizophrenia (4 papers, 2009 to 2019). A major psychotic disorder characterized by abnormalities in the perception or expression of reality. "The EXOC4 gene which can cause schizophrenia in humans, is crucial for producing insulin and involved in protein and hormone metabolism." (PMID 31600309, 2019). "The network constructed from four schizophrenia risk markers suggests that EXOC4 might be a novel marker for this disease." (PMID 19379523, 2009). "The interactions among DTNBP1, DLG4 and EXOC4 are present in various brain tissues, such as prefrontal cortex and temporal lobe, which are known to be related to schizophrenia etiology." (PMID 19379523, 2009). "The GRIN2B and EXOC4 genes have been found to be in relation to schizophrenia." (PMID 30034349, 2018). "The roles of DLG4 and EXOC4 in schizophrenia remain to be explored, and the two genes might serve as putative risk markers with potential for further studies." (PMID 19379523, 2009). "Similarly, EXOC4 is known to be involved in the exocyst complex, which is critical for the release of neurotransmitters; at present its functional involvement in schizophrenia is unknown." (PMID 19379523, 2009).
ciliopathies (3 papers, 2020 to 2025). "Mutations or deletions in genes encoding exocyst proteins, including EXOC2, EXOC4, EXOC7, and EXOC8, have been associated with ciliopathies and neural developmental disorders." (PMID 40777261, 2025).
diabetes (2 papers, 2008 to 2020). "Association analyses to diabetes using SNPs in the EXOC4 and LRGUK gene regions identified multiple polymorphisms with evidence for association." (PMID 18498660, 2008). "Using a dominant modeling of the minor allele, the SNP rs12531707 in an EXOC4 intron produced an odds ratio for diabetes of 1.79 (p = 0.009)." (PMID 18498660, 2008). "Genes LRGUK and EXOC4 in ROH island on CHA14 are associated with diabetes and fasting glucose in human, and could be associated with endurance in this dog breed as it was shown that fasting glucose is significantly correlated with the intensity of the training regimen in professional athletes." (PMID 33139624, 2020).
Obesity (2 papers, 2019 to 2021). Accumulation of substantial excess body fat. "Therefore, EXOC4 may play a role in signal transmission from sensory perception to the brain, thus affecting obesity." (PMID 31118946, 2019). "In the present study, our GWIA for BMI found an interaction between EXOC4 and 1q23.1 that may contribute to the development of obesity, although this interaction did not pass the Bonferroni correction test, they had the lowest interaction P-value (P = 4.05 × 10-13) after accidental exclusion." (PMID 31118946, 2019).
Stroke (2 papers, 2022 to 2025). Sudden impairment of blood flow to a part of the brain due to occlusion or rupture of an artery to the brain. "The results from the pathway analysis from proteins differentially expressed linked with EXOC4 methylation, suggested that the inflammatory pathway, regulated by NK cells, could be involved in the regulation of stroke outcome by methylation." (PMID 36180927, 2022). "DNA methylation of EXOC4 is associated with a worse neurological course after stroke." (PMID 36180927, 2022). "Another possible hypothesis for the association of EXOC4 methylation and stroke outcome is the affectation of the glutamate receptors dynamism." (PMID 36180927, 2022). "Despite the differences between both cohorts, we have been able to replicate the results, which reinforces the plausible implication of EXOC4 methylation in stroke outcome." (PMID 36180927, 2022). "Considering that our results indicated that EXOC4 methylation is associated with a decrease in the expression of EXOC4 and with worse neurological course, we hypothesize that Sec8 could be regulating the trafficking of synaptic glutamate receptors related to cell survival in stroke." (PMID 36180927, 2022). "The excitotoxicity, neuroinflammatory and the synaptic regulation are pathways that have been suggested to be pathological mediators of ischaemic brain damage and could be potentially regulating the link between the methylation in EXOC4 and the stroke outcome." (PMID 36180927, 2022). "The higher methylation in cg00039070 identified in patients with a worse stroke outcome could be mediated by the decrease in the EXOC4 expression." (PMID 36180927, 2022). "The results indicated that the effect of the EXOC4 methylation in brain could be specific for some brain regions and its effect could be exacerbated in patients with stroke." (PMID 36180927, 2022).
breast carcinoma (1 paper, 2010). "The protein EXOC4 is part of the exocyst complex that has been implicated in breast cancer invasiveness." (PMID 20126641, 2010).
dyslexia (1 paper, 2013). A learning disorder characterized by an impairment in processing written words. "Interestingly, regions near to 7q33, containing the gene EXOC4, has previously been linked to speech and language disorders and dyslexia." (PMID 23460800, 2013).
glaucoma (1 paper, 2018). Increased pressure in the eyeball due to obstruction of the outflow of aqueous humor. "We verified the European glaucoma gene TXNRD2 andidentified a novel candidate locus encompassing EXOC4 that requiresfurther follow up in large African studies." (PMID 30317457, 2018).
hydronephrosis (1 paper, 2022). Collection of urine in the renal pelvis that results in dilatation of the renal pelvis and calyces. "Exoc4/Sec8-/- mice initiate gastrulation but die shortly afterward, Exoc1/Sec3-null mice undergo peri-implantation lethality, and the conditional ablation of Exoc5/Sec10 leads to bilateral hydronephrosis and complete anuria in newborn mice leading to death shortly after." (PMID 36150098, 2022).
lymphoma (1 paper, 2023). A malignant (clonal) proliferation of B- lymphocytes or T- lymphocytes which involves the lymph nodes, bone marrow and/or extranodal sites. "EXOC4 does not currently have a clear role in lymphoma, but it may be involved by sensitising lymphoma cells to doxorubicin or affecting Bcl-2 transcription." (PMID 37756103, 2023).
Meckel-Gruber syndromes (1 paper, 2022). "In addition mutations in EXOC8 and EXOC4 have been implicated in Joubert and Meckel-Gruber syndromes, respectively." (PMID 36150098, 2022).
nephrotic syndrome (1 paper, 2023). A collection of symptoms that include severe edema, proteinuria, and hypoalbuminemia; it is indicative of renal dysfunction. "Mutations in EXOC8 and EXOC2 are associated with neurodevelopmental disorders, and mutations in EXOC6B with skeletal abnormalities and mutations in EXOC4 have been associated with nephrotic syndrome." (PMID 36920342, 2023).
cancer (3 papers, 2019 to 2025). A tumor composed of atypical neoplastic, often pleomorphic cells that invade other tissues. "These modules contained several cancer regulators such as Intraflagellar Transport (IFT) complex proteins (IFT74, IFT88), BBSome complex proteins (BBS2, BBS7, BBS9, BBS12), exocyst complex components (EXOC3, EXOC4, EXOC6B, EXOC7, and EXOC8), TTC8, TTC21B, EVC, and NEK1." (PMID 40700427, 2025). "However, TNBC, HER2-enriched and luminal B cancers additionally included exocyst-associated markers (EXOC3, EXOC4, EXOC6B, EXOC7, and EXOC8), which suggested that, unlike luminal A, these cancers not only share dysregulation of ciliogenesis but also dysfunction of transport to cilium." (PMID 40700427, 2025).
neurodevelopmental disorder (2 papers, 2023 to 2024). A behavioral and cognitive disorder with onset during the developmental period that involves impaired or aberrant development of intellectual, motor, or social functions. "Defects in the human homologues of yeast SEC5 (corresponding to human EXOC2), SEC6 (EXOC3L2), SEC8 (EXOC4), SEC15 (EXOC6B), EXO70 (EXOC7), EXO84 (EXOC8), and RHO3 (RALA) are associated with a variety of neurodegenerative and neurodevelopmental disorders." (PMID 39560727, 2024).
myopathy (1 paper, 2022). A disease of the muscle in which the muscle fibers do not function properly. "Forty-six candidate genes are prioritized by multiple approaches (42 for LST and 6 for MVPA; 2 overlap) and point to endocytosis (CNIH2, RAB1B, KLC2, PACS1, REPS1, DNM3, EXOC4), locomotion (CADM2, KLC2) and myopathy (MLF2, HERC1, KLC2, SIL1) as relevant pathways." (PMID 36071172, 2022).
EXOC4 also shares sentences with these, for which no sentence is quoted: Joubert syndrome (2 papers); metabolic syndrome (2); tumor (2); acute promyelocytic leukemia (1); Alzheimer disease (1); Carpenter syndrome (1); cognitive decline (1); Cognitive impairment (1); colorectal cancer (1); cyst (1); infection (1); language disorder (1); mental disorder (1); multicystic dysplastic kidney (1); neuroblastoma (1); neurological disorders (1); oral squamous cell carcinoma (1); type I multiple exostoses (1).